CC2D2B (coiled-coil and C2 domain containing 2B)
Synonyms: C10orf130; C10orf131; bA248J23.4; bA690P14.3
Tractability: No criterion of Open Targets' tractability assessment is met for any kind of drug.
Gene: Protein-coding gene on chromosome 10 (95,907,603 to 96,033,745, forward strand). Ensembl gene ENSG00000188649.
Subcellular location (Human Protein Atlas): Nucleoplasm; Basal body; Cytosol; Vesicles
Gene Ontology:
Biological process: non-motile cilium assembly; protein localization to ciliary transition zone
Cellular component: ciliary transition zone
Genetic constraint (gnomAD): Loss-of-function variants: 25 observed, 41.98 expected, observed/expected ratio (o/e) 0.6, 90% interval 0.43 to 0.83. The upper end of that interval is the gene's LOEUF score, 0.83, which puts it in group 3 of 6, group 1 being the genes least tolerant of losing a copy. Missense variants: 368 observed, 446.45 expected, observed/expected ratio (o/e) 0.82, 90% interval 0.76 to 0.9. Synonymous variants: 128 observed, 154.7 expected, observed/expected ratio (o/e) 0.83, 90% interval 0.72 to 0.96.
Homologues: Orthologues: rabbit CC2D2B (81% identical), pig CC2D2B (80% identical), rat Cc2d2b (75% identical), mouse Cc2d2b (74% identical), chimpanzee CC2D2B (73% identical), Drosophila melanogaster Cc2d2a (19% identical), Caenorhabditis elegans mks-6 (19% identical). Paralogues in human: CC2D2A (38% identical), CEP76 (10% identical).
Diseases named in the same sentence as CC2D2B in open-access papers:
CC2D2B is named in the same sentence as 3 diseases in open-access papers, as found by Europe PMC text mining. Sharing a sentence is not in itself a finding about the gene and the disease. The quoted sentences say what the papers report.
COVID-19 (1 paper, 2024). A disease caused by infection with severe acute respiratory syndrome coronavirus 2. "DAW1, ESF1, KCTD2, USP45, PNMA8A, SYNDIG1L, and CC2D2B are novel genes/proteins that may be linked to COVID-19." (PMID 38674024, 2024).
CC2D2B also shares sentences with these, for which no sentence is quoted: papillary thyroid carcinoma (1 paper); periodontitis (1).